FBXO7 (F-box protein 7)
Diseases named in the same sentence as FBXO7 in open-access papers (continued):
Sharing a sentence is not in itself a finding about the gene and the disease.
neurodegenerative disease (8 papers, 2011 to 2024). A disorder of the central nervous system characterized by gradual and progressive loss of neural tissue and neurologic function. "One of the functions of the SCF complex is to eliminate misfolded proteins, and various components of the complex (SKP1, Cullin1, FBXL5, FBXO7, FBXL18, Parkin) have been associated with neurodegenerative diseases." (PMID 34709416, 2021). "Furthermore, three novel pathogenic FBXO7/PARK15 mutations in two families were recently reported, showing unambiguously that recessive mutations in the gene encoding the F-box protein 7,FBXO7 cause a neurodegenerative disease with early onset, parkinsonian–pyramidal phenotype." (PMID 37644186, 2024).
nervous system diseases (2 papers, 2016 to 2023). "Notably, Fbxo7 and members of the LanC-like family have been shown to impact similar neurological disorders." (PMID 27936058, 2016).
autosomal recessive disease (1 paper, 2012). Autosomal recessive form of disease. "PARK15 is an autosomal recessive disease, caused by the loss of function of the proteins encoded by the FBXO7 gene, and in particular, by the loss of the function of the longer FBXO7 isoform (isoform 1), which localizes in the cell nucleus." (PMID 23133663, 2012).
movement disorder (1 paper, 2021). Neurological conditions resulting in abnormal voluntary or involuntary movement, which may impact the speed, fluency, quality and ease of movement. "This Movement Disorder Society Genetic mutation database Systematic Review focuses on monogenic atypical parkinsonism with mutations in the ATP13A2, DCTN1, DNAJC6, FBXO7, SYNJ1, and VPS13C genes." (PMID 34396589, 2021).
psychiatric disorder (1 paper, 2025). A disorder characterized by behavioral and/or psychological abnormalities, often accompanied by physical symptoms. "Several genes—including ATP6V1B2, FBXO7, PHF23, and WDR6—consistently emerged as risk factors in multiple conditions, suggesting that dysregulation of autophagy-related or immune-modulatory pathways may contribute broadly to the development of inflammatory and psychiatric disorders." (PMID 41595424, 2025).
FBXO7 also shares sentences with these, for which no sentence is quoted: Dystonia (3 papers); Ataxia (2); breast cancer (2); colon cancer (2); blood cancers (1); blood disorders (1); clear cell renal cell carcinoma (1); colon adenocarcinoma (1); colorectal cancer (1); Encephalopathy (1); hereditary ataxia (1); infection (1); infertile (1); Kufor-Rakeb syndrome (1); leukoplakia (1); lymphoid cancer (1); melanoma (1); ovarian tumors (1); proteinopathies (1); Psychosis (1); renal carcinoma (1); tauopathies (1).